ERAP1 (endoplasmic reticulum aminopeptidase 1)
Diseases named in the same sentence as ERAP1 in open-access papers (continued):
Sharing a sentence is not in itself a finding about the gene and the disease.
tumor (continued). "For example, patients expressing hyperactive ERAP1 might be likely to mount better responses to overtrimmed tumor-derived epitopes if given ERAP1 inhibitors, and conversely those expressing hypoactive allotypes if given ERAP1 activators." (PMID 29599287, 2018). "Recently, the lack of ERAP1 expression in tumor cells was suggested to correlate with an enhanced ability of NK cells to efficiently kill ERAP1 deficient tumor cells, possibly due to lack of regulatory MHC class I/Ly49C interactions." (PMID 23894499, 2013). "Therefore, the regulation of ERAP1 in activating the ligands on tumor cells and inhibitory receptors on NK cells could signal development for NK cell-based immunotherapy." (PMID 36834865, 2023). "Indeed, Reeves and colleagues demonstrated that the functional activity of different ERAP1 allotypes is positively correlated with the amount of tumour-infiltrating CD8+ T cells in HPV+ oropharyngeal squamous cell carcinomas (OPSCC) through the generation of HPV E6/E7 epitopes." (PMID 35936007, 2022). "However, the effect of ERAP1 inhibition in tumor cells was highly variable, suggesting that its efficacy may depend on several factors, including MHC class I typing." (PMID 34917091, 2021). "However, the effect of ERAP1 inhibition in tumor cells and LCLs was highly variable, suggesting that it may depend on MHC class I typing and/or ERAP1 genotype." (PMID 34917091, 2021). "It is also possible that naturally processed epitopes within the tumor could be aberrantly processed or trimmed by the endoplasmic reticulum aminopeptidase 1 (ERAP1) protein within the endoplasmic reticulum (ER), leading to degenerate, non-immunogenic MHC-I-compatible sequences." (PMID 29731959, 2018). "Additionally, the function of ERAP1 in regulating inflammatory cytokine production may contribute to these effects by influencing the inflammatory state of the tumor microenvironment." (PMID 25566501, 2014). "In this case, down-regulation of ERAP1 may lead to the preferential loading and presentation of non tumor-associated or non HPV-associated peptides, thereby yielding a less immunogenic phenotype and facilitating tumor growth and progression." (PMID 22942706, 2012). "Taken together, our findings suggest that modulation of ERAP1 activity can generate unique immunopeptidomes, mainly due to altered peptide processing in the ER, but also induce changes in the cellular proteome and metabolic state which may have further effects on tumor cells." (PMID 40189142, 2025). "Our data suggest that ERAP1 activity, while highly specialized for antigen presentation, is also important for ER peptide homeostasis and may therefore play a dual role in metabolic adaptations of tumor cells attempting to evade the innate and adaptive immune response." (PMID 40189142, 2025). "Additionally, we checked whether some ERAP1 SNPs, which were found to be associated with NSCLC predisposition (as shown in our last report), correlated with ERAP1 mRNA levels in tumor and adjacent non-tumor tissue." (PMID 37101107, 2023). "ERAP1 and ERAP2’s structure, location, and function implicate their potential impact on the irregular peptides, and HLAs found in trophoblast and tumor cells." (PMID 36834865, 2023). "ERAP1 and ERAP2 trim peptides for antigen presentation on HLA class I molecules within the ER, which is crucial in tumor cell and immune system interactions." (PMID 36834865, 2023). "The endoplasmic reticulum (ER) aminopeptidases ERAP1 and ERAP2 are two frequently altered genes that affect anti-tumor immune responses and tumor growth." (PMID 35418980, 2022). "We detected ERAP1 and ERAP2 expression in tumor cells and cells in the microenvironment in primary HL tissue samples." (PMID 33499248, 2021). "Animal model studies have shown that altered levels of ERAP1 and ERAP2 can facilitate tumor immune evasion." (PMID 29552294, 2018).
tumor (continued). "We have shown that ERAP1 overtrimming can have a significant impact on anti-tumor immunity in a preclinical model, where reduction of ERAAP protein in the murine CT26 tumor significantly increased generation of the immunodominant cryptic epitope." (PMID 29599287, 2018). "The availability of specific ERAP1 and ERAP2 antibodies has allowed researchers to investigate the expression and tissue distribution of these enzymes in a large number of tumor cells of various origins." (PMID 25566501, 2014). "The enzymatic activity and expression levels of the mouse homolog of ERAP1, ERAAP, have been demonstrated to be key for the immune evasion of tumor cells in two distinct murine models." (PMID 25566501, 2014). "ERAP1 silencing in T cell lymphoma RMA results in tumor rejection in syngeneic mice by triggering NK cells and subsequently T cell (CD4+ and CD8+) anti-tumor responses." (PMID 25566501, 2014). "Taken together, these studies suggest that normal function of ERAP1 and ERAP2 is required for NK cell- and T cell-mediated anti-tumor immunity." (PMID 25566501, 2014). "In conclusion, we explored a non-toxic approach based on ERAP1 inhibition and entinostat treatment to increase the immunogenicity of NB by making tumor responsive to PD-1 blockade." (PMID 39438988, 2024). "Altogether, these data demonstrate that the lack of ERAP1 enhances the efficacy of combination therapy with entinostat and anti-PD-1 in a tumor model such as 9464D, that is basically unresponsive to PD-1 blockade." (PMID 39438988, 2024). "We observed a significantly lower level of ERAP1 mRNA expression in tumor tissue (MedTumor = 0.75) in comparison to non-tumor tissue (MedNon-tumor = 1.1), p = 0.008." (PMID 37101107, 2023). "It is worth noting that our results suggest that ERAP1 expression in tumor tissue does not seem to be under the direct or indirect control of rs26653, in contrast to what we observed in adjacent normal tissue." (PMID 37101107, 2023). "Using real-time qPCR, we evaluated ERAP1 mRNA expression in samples of tumor and adjacent non-tumor tissue (serving as control tissue) from 61 NSCLC patients." (PMID 37101107, 2023). "The authors detected ERAP1 in normal lung bronchial epithelium and myoepithelium, but none of the ten tumor specimens tested were ERAP1 positive." (PMID 37101107, 2023). "In our study, the ERAP1 expression level detected in the tumor tissue as well as in the adjacent normal tissue did not affect the overall survival of NSCLC patients." (PMID 37101107, 2023). "In conclusion, we showed that ERAP1 mRNA expression in the non-tumor tissue was significantly higher than in tumor tissue from the same patient." (PMID 37101107, 2023). "The expression of ERAP1 is frequently altered in tumors, when compared to normal, non-cancerous tissues, but how this affects tumor growth and the activation of anti-tumor immune responses is still not understood well." (PMID 37101107, 2023). "Fhit-transfected B11 tumor cells had increased transcriptional levels of the following genes: Fhit, H-2 class I heavy chains, β2-microglobulin, Tap-1, Tap2, LMP2, LMP10, Tapasin, calreticulin, Erap1, ERp57, PA28α, Ttp1, and Ttp2." (PMID 32545680, 2020). "Western blot analysis of tumor tissues showed upregulation of ERAP1 following treatment with pre-siiRhom, alone or in combination with DOX, suggesting that iRhom1 KD may similarly improve antitumor immune response through upregulation of ERAP1 in vivo." (PMID 38177179, 2024). "To test whether the effect of ERAP1 inhibition on 9464D cells is masked by the low expression levels of MHC class I molecules, we evaluated the efficacy of entinostat in upregulating the expression of MHC class I molecules in our tumor model." (PMID 39438988, 2024). "Therefore, the absence or presence of ERAP1 and ERAP2 could change the peptide repertoire of trophoblast or tumor cells, increasing immune tolerance and allowing for increased proliferation and invasion." (PMID 36834865, 2023).
tumor (continued). "While it was documented that the expression of ERAP1 and ERAP2 is frequently altered in tumors compared to that in normal cells, only a few investigations have been conducted on how the altered expression of ERAP genes affects tumor growth and anti-tumor immune response." (PMID 36834865, 2023). "In that case, the detection of the effects of ERAP1 SNPs also in smokers may be explained by the contribution of peptide trimming by this enzyme to production of tumor antigenic epitopes different in smokers and never-smokers." (PMID 36741370, 2022). "However, to date the mechanisms leading to ERAP1 downregulation in this tumor type have not been elucidated." (PMID 26146606, 2015). "Notably, upregulation of ERAP1 and ERAP2 in ERAP-low tumor cells was found to enhance HLA class I surface expression, suggesting that abnormal HLA class I levels in tumor cells may result from defective expression of these enzymes." (PMID 25566501, 2014). "In addition a set of 15 proteins that participate in the antitumor immune response such as the tumor suppressors PSMB9, ERAP1 and TAP1 or the interferon-stimulated genes IFIT1 and MX1 were found down-regulated in CUL4A-overexpresing cells and up-regulated in CUL4A-silencing models." (PMID 24870930, 2014). "It is therefore possible that inhibition of ERAP1, by generating a novel immunopeptidome, may be a viable therapeutic strategy to enhance anti-tumor immune responses in non-immunogenic tumors, such as NB, in combination with a treatment that enhances the surface expression of MHC class I molecules." (PMID 39438988, 2024). "The level of ERAP1 mRNA expression did not affect the overall survival of patients with NSCLC, either in the case of the tumor (p = 0.788) or in non-tumor (p = 0.298) tissue." (PMID 37101107, 2023). "The levels of ERAP1 mRNA expression did not affect the overall survival of NSCLC patients, either in the case of the tumor (p = 0.788) or in non-tumor (p = 0.298) tissue." (PMID 37101107, 2023). "ERAP2 also influenced the recognition of the gp100209–217 tumor epitope and enhanced T-cell recognition of the MART-126/27–35 epitope in the absence of ERAP1." (PMID 38067336, 2023). "The expression and tissue distribution of ERAP1 and ERAP2 have been evaluated in a large number of tumor cells of lymphoid and non-lymphoid origin compared to their normal counterparts." (PMID 22942706, 2012).
infection (18 papers, 2012 to 2025). The state of being infected such as from the introduction of a foreign agent such as serum, vaccine, antigenic substance or organism. "ERAP1 expression was interfered in 221 parental and transfectant cells by infection with lentiviral particles encoding small hairpin RNA targeting human ERAP1 (shERAP1) or a control sequence (shCTRL)." (PMID 34917091, 2021). "Another recent case-control study assessed the impact of ERAP1 allotypes on virus-specific CD8+ T-cell response in a human leukocyte antigen (HLA)-B*27:05+ individual with acute HCV-infection." (PMID 32183384, 2020). "Previous studies suggest that variations in ERAP1 can alter clinical outcome in certain infections." (PMID 38980912, 2024). "Interestingly, the level of genes encoding peptidases (Tpp1, Tpp2, Nrd1, Erap1), which are known to be required for the generation of most MHC class I-binding peptides, were decreased after infection." (PMID 36318581, 2022). "As ERAP1 and ERAP2 play a critical role in shaping these suitable-sized peptides, polymorphisms in their gene sequence can significantly affect the produced antigenic repertoire, thus conditioning infection chronicity as demonstrated for HCV infection." (PMID 32183384, 2020). "While the geographic distribution of rs27895 considering the history of IAV pandemic origins and our association and functional data suggests that variation in ERAP1 may have helped humans adapt to IAV infection, human evolution of complex cellular phenotypes of infection are undoubtedly polygenic." (PMID 36465279, 2022). "According to these results, the authors assumed that the rs26618 polymorphism may affect either the enzymatic activity or the structure of ERAP1, leading to alterations in the HCV antigen presentation pathway, and in turn to increased susceptibility to this infection." (PMID 32183384, 2020). "The lack, or downregulation of ERAP1 expression upsets the antigen-presenting properties and immunological function of MHC class I molecules in the host defense against infection." (PMID 38024089, 2023). "We tested both TNFSF12 and ERAP1 for a role in regulating IAV infection by reducing expression with small interfering RNA (siRNA) and assessing infection using an IAV mNeon reporter strain." (PMID 36465279, 2022). "The endoplasmic-reticulum aminopeptidase ERAP1 processes antigenic peptides for loading on MHC-I proteins and recognition by CD8 T cells as they survey the body for infection and malignancy." (PMID 34489420, 2021). "We extended our earlier study to determine whether variation in ERAP1 and ERAP2 influences infection outcome." (PMID 38980912, 2024). "Furthermore, increased levels of TAP-transporters (TAP1, TAP2), MHC I components B2M and HLAs, together with the ER chaperons calreticulin (CALR) and calnexin (CALN), and aminopeptidases ERAP1 and ERAP2 indicated upregulation of MHC I dependent antigen presentation with progressing infection." (PMID 37112941, 2023).
infectious disease (7 papers, 2012 to 2023). A disorder directly resulting from the presence and activity of a microbial, viral, or parasitic agent in humans. "In presented cohort of the DRPs, we also found endoplasmic reticulum aminopeptidase 1 (ERAP1), which is primarily responsible for the generation of the antigenic repertoire presented by MHC-I molecules, in the control of susceptibility of different infectious diseases." (PMID 34673282, 2021). "In this review, we have summarized the recent knowledge on the biology of ERAP1 and ERAP2 enzymes and their possible links to several infectious diseases." (PMID 32183384, 2020). "The investigation of epistasis interaction between ERAPs and HLA variants is also essential in order to properly disclose the mechanism through which ERAP1 and ERAP2 influences infectious diseases and the process of antigen presentation." (PMID 32183384, 2020). "Because ERAP1 also contributes to shedding the membrane-bound receptor for inflammatory cytokines including IL1R2, TNFR1, and IL6R, ERAP1 is likely to play a pivotal role in protection from infectious diseases, in maintaining immunotolerance, and in controlling inflammation." (PMID 22253828, 2012).
bacterial infections (1 paper, 2024). "In addition, viral and also perhaps bacterial infections induce, in rs2248374G individuals, the expression of a third truncated transcript giving a shortened protein devoid of enzymatic activity but nevertheless possibly capable of interfering with ERAP1 and ERAP2 function." (PMID 39906739, 2024).
ERAP1 also shares sentences with these, for which no sentence is quoted: multiple sclerosis (6 papers); birdshot chorioretinopathy (5); Crohn disease (4); juvenile idiopathic arthritis (3); essential hypertension (2); hepatitis B infection (2); iridocyclitis (2); renal carcinoma (2); acute myeloid leukemia (1); adenocarcinoma (1); alcohol dependence (1); allergic rhinitis (1); amyloidosis (1); anterior uveitis (1); brain tumor (1); Cataplexy (1); Cirrhosis (1); deafness (1); enthesitis related arthritis (1); frontal fibrosing alopecia (1); gastric adenocarcinoma (1); HELLP syndrome (1); hepatitis C (1); inflammation (1); insulin-dependent diabetes mellitus (1); juvenile psoriatic arthritis (1); liver cancer (1); lung squamous cell carcinoma (1); lymphoma (1); metastatic melanoma (1).
A further 14 diseases each share a sentence with ERAP1 in 1 paper.